KEAP1 (kelch like ECH associated protein 1)
Diseases named in the same sentence as KEAP1 in open-access papers (continued):
Sharing a sentence is not in itself a finding about the gene and the disease.
ovarian carcinoma (continued). "By looking at the KEAP1 regulation side, miR-141 was the first reported miRNA to target KEAP1 by binding to its 3′-UTR sequence site in ovarian carcinoma cell lines." (PMID 29643973, 2018). "The NRF2/KEAP1 pathway is a key regulator of cellular responses to oxidative stress in several ovarian cancer models, and has been shown to be influenced by auranofin treatment." (PMID 29599910, 2018). "The same phenomenon of markedly elevated Keap1 levels during the NACT was recently detected in ovarian cancer patients." (PMID 29348788, 2017). "In human ovarian cancer cells, p62 efficiently regulated the Keap1–Nrf2–ARE system to mediate cisplatin resistance, avoiding oxidative stress‐induced apoptosis." (PMID 27758045, 2016). "Another study showed that the overexpression of p62 may protect cells from oxidative damage by activating the Keap1-Nrf2-ARE signalling pathway in ovarian cancer." (PMID 39857448, 2025). "Additionally, NRF2 and KEAP1 basal levels are cell line specific and positively correlate both to cell growth rates and basal ROS, in the following ovarian cancer cell lines: PEO1, PEO4, PEO6, SKOV3, OVCAR3 and OVCAR4." (PMID 35453348, 2022). "As concerning KEAP1, miR-141 was the first identified miRNA to directly repress its levels in ovarian carcinoma cell lines while the same miRNA was later shown to confer 5-FU resistance in HepG2 cells, an alteration phenocopied by miR-141 mimics and partially reversed by the reintroduction of KEAP1." (PMID 31097977, 2019). "Moreover, we illustrated that while knockdown of NRF2 significantly sensitised ovarian cancer cells to targeted immunotherapy, parallel knockdown of KEAP1 reversed this sensitisation." (PMID 26770651, 2016). "Half of ovarian carcinomas with positive nuclear Nrf2 staining had either Keap1 mutations or absent Keap1 mRNA expression resulting in platinum resistance." (PMID 28983331, 2015). "Finally, we explored whether factors such as ATF4, GPX4, GSS, KEAP1, NFE2 like BZIP transcription factor 2 (NEF2L2), SLC7A11, SQSTM1, ATG3, ATG4D, and ATG5 have potential as non-invasive diagnostic markers for ovarian cancer." (PMID 37215446, 2023). "Thus, we speculate that OGT can regulate KEAP1/NRF2 through glycosylation in ovarian cancer cells to regulate the cisplatin resistance of OC cells." (PMID 34876558, 2021). "However, the regulatory mechanism of Keap1-Nrf2 pathway in ovarian cancer is still unclear 13-15." (PMID 32047536, 2020). "Moreover, epigenetic alterations in Keap1, such as Keap1/Cul3 hypermethylations, are responsible for the accumulation and aberrant activation of Nrf2 in lung, prostate, head and neck, colorectal, and ovarian cancer." (PMID 28475131, 2017). "However, the low reported frequency of inactivating KEAP1 mutations does not account for the reportedly high frequency of NRF2 protein activation in ovarian cancer." (PMID 25114896, 2014). "Therefore, the Keap1-Nrf2-ARE pathway may be a potential target in ovarian cancer therapy, and by inhibiting Nrf2 activity or interfering with its signalling pathway, the efficacy of chemotherapeutic agents may be improved and the resistance of tumour cells reversed." (PMID 39857448, 2025). "The results of cDNA expression profile analysis indicated that six genes, including GPX4, GSS, KEAP1, SQSTM1, SLC7A11, ATG3, and ATG5, were highly expressed in tumor tissues from patients with ovarian cancer." (PMID 37215446, 2023). "The results of the data analysis indicated that the contents of ATF4, GPX4, GSS, KEAP1, and ATG3 in the peripheral blood exosomes of patients with ovarian cancer were significantly higher than those of the healthy controls." (PMID 37215446, 2023). "Kaplan-Meier plot analysis indicated that the expression levels of GSS, KEAP1, ATG3, and ATG4D correlated significantly and negatively with the survival of patients with ovarian cancer." (PMID 37215446, 2023).
ovarian carcinoma (continued). "In addition, it has been confirmed that miR-200a-3p/141-3p directly combined to 3′-UTR of KEAP1, thus profoundly dysregulating NRF2/KEAP1 pathway in renal tumorigenesis and ovarian cancer cells, which could be blocked by PEITC significantly to reduce the oxidative stress response." (PMID 35754474, 2022). "The results of multiple gene correlation analyses indicated that there was a significant linear relationship (positive correlation) between the expression of ATF4 in ovarian cancer tissue and the expression levels of GPX4, GSS, KEAP1, NFE2L2, SLC7A11, ATG3, ATG4D, and ATG5." (PMID 37215446, 2023). "In addition, we performed exosome database screening and found that the levels of ATF4, GPX4, GSS, KEAP1, and ATG3 in the peripheral blood exosomes of patients with ovarian cancer were significantly higher than those from the healthy controls." (PMID 37215446, 2023). "It has been shown that underexpression of RBX1, due to gene CNL, might interfere with the KEAP1/CUL3/RBX1 complex, which also displays a E3 ubiquitin-ligase activity in thyroid and ovarian cancer." (PMID 25298778, 2014). "While the magnitude and frequency of KEAP1/CUL3/RBX1 complex component disruption were more prominent in the cohort we assessed, these results reveal the potential importance of alternative mechanisms of NRF2 activation in ovarian cancer and warrant consideration in future studies." (PMID 25114896, 2014).
colitis (36 papers, 2016 to 2025). Inflammation of the colon. "According to the research, SYD mitigates acute and chronic colitis and reduces the risk of colitis‐associated CRC by modulating the Keap1–Nrf2–ARE pathway, thereby inhibiting inflammation and oxidative stress." (PMID 40119640, 2025). "This was supported by the up-regulated expression levels of Nrf2, Keap1, and GPx4 mRNA and proteins in both mice with colitis and LPS-induced MCEC cells supplemented with GSH-Se." (PMID 40076493, 2025). "The results suggested that the alleviating effects of GSH-Se on mouse colitis was likely mediated by the activation of the Nrf2/Keap1 (nuclear factor E2-related factor 2/Kelch-like ECH-associated protein 1) and GPx4 signalling pathways." (PMID 40076493, 2025). "Dehydrocostus lactone significantly ameliorated DSS-induced colitis in mice at doses of 5–15 mg/kg by covalently targeting both IKKα/β and Keap1, thereby suppressing NF-κB signaling and activating the Nrf2 pathway." (PMID 41158126, 2025). "Ultimately, the results of this investigation demonstrate that OPs effectively mitigate DSS-induced colitis by preserving the integrity of the intestinal barrier and modulating the Keap1-Nrf2 axis." (PMID 38140314, 2023). "The present study discovered miR-200a down-regulation, excessive inflammatory activation, enterocyte apoptosis, colonic dysfunction, and Keap1/Nrf2 antioxidant pathway inactivation in mouse colitis and NCM460 cells under DSS induction." (PMID 37646040, 2023). "Our previous study demonstrated that NED mitigated the proinflammatory response and activated the Keap-1/Nrf2 signaling pathway to induce potent antioxidant effects using in vivo and in vitro models of colon inflammation." (PMID 37049744, 2023). "We recently reported that NED significantly exhibited antioxidant activity by stimulating the Keap-1/Nrf2 signaling pathway and also showed potent antioxidant and anti-inflammatory activity in colon inflammation using in vivo and in vitro models." (PMID 37049744, 2023). "Overall, this study shows that OPs alleviate DSS-induced colitis by maintaining the intestinal barrier and modulating the Keap1-Nrf2 axis." (PMID 38140314, 2023). "The amelioration of DSS-induced colitis is accomplished by modulating the Keap1/Nrf2 pathway and gut microbiota." (PMID 37359553, 2023). "Rutaecarpine and carnosic acid ameliorated inflammatory responses in DSS-induced colitis mice via Nrf2 activation by interfering with Keap1-Nrf2 binding; such attempts have shown promise as emerging therapeutic strategies for IBD." (PMID 35277165, 2022). "FECs regulated the oxidative stress and inflammatory response in colon by activating the Keap1–Nrf2 pathway, which served to alleviate colitis." (PMID 36552614, 2022). "In the present study, this point contributes to the understanding of the biological activity of FECs alleviating colitis in relation to the activation of the Keap1–Nrf2 pathway." (PMID 36552614, 2022). "Above all, SFN and ISO possessed high logP values and effectively improving DSS-induced colitis by activating the Keap1–Nrf2 pathway to alleviate oxidative stress and inflammatory responses." (PMID 36552614, 2022). "An increasing number of recent studies have shown that the Keap1-Nrf2-ARE signaling pathway is closely related to colitis." (PMID 34829046, 2021). "TRL activates the Nrf2-HO-1 pathway via covalent binding to KEAP1, contributing to the amelioration of rat colitis as part of the anti-colitic activity of the drug." (PMID 34832874, 2021). "In conclusion, TRL activates the Nrf2-HO-1 pathway via covalent binding to KEAP1, contributing to the amelioration of rat colitis as part of the anti-colitic activity of the drug." (PMID 34832874, 2021). "DSS-induced colitis resulted in an increased expression of p22-phox, gp91-phox, and Keap1 in colon tissues." (PMID 31827675, 2019).
colitis (continued). "Consistently, we observed an elevation of these cytokines, including TNF-α, IL-1β, and IL-6, p-IκB, NFκB p65, p22-phox, gp91-phox, and Keap1 in colitis mice." (PMID 31827675, 2019). "Taken together, our data demonstrate that the maggot extracts exerted therapeutic effects in experimental colitis through activation of Nrf2 and degradation of Keap1." (PMID 31827675, 2019). "We found that CA prevented DSS-induced colitis by regulating the Keap1/Nrf2 pathway, ameliorating oxidative stress and inhibiting pro-inflammatory cytokine production." (PMID 28887507, 2017). "Our results showed that CA exhibited a protective role in DSS-induced experimental colitis through the regulation of the Keap1/Nrf2 pathway." (PMID 28887507, 2017). "The study reveals for the first time the differences in efficacy of different species of SH and its molecular mechanism, demonstrating that SP increases oxidative defense via the activation of the Nrf2/Keap1 pathway, therefore mitigating colitis and oxidative damage in UC mice." (PMID 40356967, 2025). "Modulation of the Keap1/Nrf2 pathway plays a preventive role in colitis." (PMID 37359553, 2023). "The mitigation of colitis via the modulation of the Keap1-Nrf2 and IKKα/β-NF-κB signaling pathways." (PMID 37359553, 2023). "To investigate whether Nrf‐2 signaling regulated DSS‐induced colitis, we detected the protein levels of Nrf‐2, Keap‐1, and HO‐1 by Western blot." (PMID 37970386, 2023). "The aim of this study was to investigate whether the alterations in the expression of miR-200a could impact the Keap1/Nrf2 pathways involved in the pathogenesis of colitis." (PMID 37646040, 2023). "In addition, rice protein peptides can alleviate DSS-induced colitis by modulating intestinal flora and modulating Keap1-Nrf2." (PMID 38140314, 2023). "This implies that Keap1 affinity energy and electrophilic index had less effect on the bioactivity of FECs to alleviate colitis as long as they were within an appropriate range, while the permeability represented by logP value was an important prerequisite for the bioactivity of FECs." (PMID 36552614, 2022). "Our data confirmed that 25 μM H2O2 pretreated MSC-CM treatment could effectively improve intestinal mucosal repair in experimental colitis, which may be achieved by activating Nrf2/Keap1/ARE pathway." (PMID 36456585, 2022). "These polyphenols and their metabolites could alleviate DSS induced colitis in mice by activating the Keap1-Nrf2-ARE signaling pathway, regulating gut microbiota, and increasing the level of SCFAs." (PMID 34829046, 2021). "Therefore, BGF is supposed to restore the redox balance, at least partially, through the activation of Keap1/Nrf2 signaling pathway, thereby suppressing the oxidative stress and inflammatory response and impeding the exacerbation of colitis injury." (PMID 32116661, 2019). "Over the years, related studies on the involvement of the Keap1/Nrf2 axis in the process of UC have found that mice lacking Nrf2 exhibit heightened vulnerability to dextran sodium sulfate (DSS)-induced colitis and an increased susceptibility to colorectal cancer." (PMID 37359553, 2023). "Therefore, GPH extracts may restore oxidative balance and alleviate colitis by activating the Keap1/Nrf2 signaling pathway, which may be related to the rich polyphenols in the extracts." (PMID 34829046, 2021). "By activating the Nrf2/Keap1 pathway, LWE offers robust protection against oxidative stress, significantly contributing to the progression of colitis." (PMID 39061864, 2024). "Among the six investigated FECs, the highest Keap1 affinity energy and lowest electrophilic index of SFN notwithstanding, it exhibited the strongest improvement effect in colitis." (PMID 36552614, 2022). "Our research showed that Forsythia suspensa extract can increase the protein and gene expression levels of Keap1, HO-1, Nrf2 and NQO1 in mice with colitis." (PMID 35326124, 2022).
colitis (continued). "Our results suggest that TRL activated the Nrf2-HO-1 pathway via covalent binding to KEAP1, partly contributing to TRL amelioration in rat colitis." (PMID 34832874, 2021). "In general, the up-regulation of the Nrf2/Keap1 and GPx4 signalling pathways may be one of the pivotal mechanisms by which GSH-Se alleviates DSS-induced colitis." (PMID 40076493, 2025). "The logP values, rather than the Keap1 affinity energy and electrophilic indexes of FECs, showed a strong correlation with colitis improvements." (PMID 36552614, 2022). "Mice with DSS-induced colitis exhibited substantially decreased expression of Nrf2, HO-1, and NQO-1 and increased expression of Keap1 in colon tissues; however, the expression of these proteins was significantly improved only after 25 μM H2O2-preconditioned MSC-CM treatment." (PMID 36456585, 2022). "Many studies have shown that UC is related to the Keap1-Nrf2-ARE signaling pathway, and activation of Nrf2 may be an alternative strategy for the treatment of colitis." (PMID 34829046, 2021). "However, LH011 or SASP could effectively decrease the protein level of Keap1 and further increase the protein levels of Nrf2 and HO-1 in DSS-induced colitis." (PMID 36238566, 2022). "Hence, in the present study, we characterized the main phenolic substances in green pea hull (GPH) extracts by UHPLC-LTQ-OrbiTrap-MS, and assessed the effects of GPH phenolic extracts on UC and gut microbiota based on the Keap1-Nrf2 signaling pathway, using a DSS-induced mouse colitis model." (PMID 34829046, 2021).
gastric cancer (34 papers, 2017 to 2025). A primary or metastatic malignant neoplasm involving the stomach. "The clinic pathological parameters of TCGA-derived gastric cancer patients were further analyzed and results showed that higher Keap1 expression was associated with advanced T stage." (PMID 30811526, 2019). "One pivotal study demonstrated that activating ferroptosis can alleviate cisplatin resistance in gastric cancer cells by inhibiting the Nuclear factor erythroid 2-related factor 2/Kelch-like ECH-associated protein 1/Cystine/glutamate transporter (Nrf2/Keap1/xCT) signaling pathway." (PMID 40765835, 2025). "Subsequently, activation of the Nrf2/Keap1 pathway may relieve the inhibition of ATF3 in gastric cancer cells, indicating that ATF3 is likely to cause ferroptosis through Nrf2 to imbalance the antioxidant system in gastric cancer cells." (PMID 40959280, 2025). "An examination of the mechanisms demonstrated that TCF7L1 could positively regulate antioxidant response in gastric cancer cells by positively regulating Keap1/NRF2 [Kelch-like ECH-associated protein 1/nuclear factor (erythroid-derived 2)-like 2] pathway." (PMID 30811526, 2019). "Similarly, multiple stomach cancer samples that have sequence identified somatic mutations in WDR23 have increased KEAP1 expression, ranging from 2.07 to 3.41 fold." (PMID 28453520, 2017). "Thus, it is vital to perform high-throughput assay to identify TCF7L1-interacting partners, especially those participating in chromatin modification and epigenetic regulation, to explore the mechanisms underlying epigenetic regulation of Keap1 in gastric cancer." (PMID 30811526, 2019). "DpdtbA (2,2′-di-pyridineketone hydrazone dithiocarbamate butyric acid ester) can promote ferrroptosis of gastric cancer cells through with Keap1/Nrf2/HMOX." (PMID 38503948, 2025). "It is suggested that inhibiting NEK2 to promote HMOX1 transcription through Keap1/Nrf2 was an important mechanism to affect ferroptosis in gastric cancer cells." (PMID 38503948, 2025). "It was found that FAM117B promotes the growth of gastric cancer by targeting the KEAP1/NRF2 signaling pathway." (PMID 41542087, 2025). "In the context of investigating gastric cancer drug resistance, research has demonstrated that the upregulation of the KEAP1/NRF2 signaling pathway significantly diminishes the sensitivity of gastric cancer cells to fluorouracil (5-FU) and oxaliplatin." (PMID 38370477, 2024). "Concomitantly, in the gastric carcinoma cells studied here, we were able to detect a vorinostat-mediated inhibition of Keap1 on both the protein and the mRNA level, suggesting effects on the transcript to play a role as well." (PMID 39204185, 2024). "FAM117B activates KEAP1/NRF2 signaling by decreasing ubiquitin-proteasome degradation of NRF2 in gastric cancer cells." (PMID 36719368, 2023). "Overall, CEP can induce oxidative stress by regulating Nrf2/Keap1 and alter energy metabolism, resulting in anti-gastric cancer effects." (PMID 38086844, 2023). "In summary, this research reveals that CEP regulates energy metabolism to inhibit cell growth and responds to oxidative stress by regulating the Keap1-Nrf2 axis, which results in cell cycle arrest and apoptosis in gastric cancer cells." (PMID 38086844, 2023). "Considering that KEAP1/NRF2 signaling is regulated by multiple mechanisms in tumor cells, further studies are needed to determine the importance of FAM117B-mediated regulation of KEAP1/NRF2 signaling in gastric cancer." (PMID 36719368, 2023). "FAM117B promotes the chemoresistance of gastric cancer cells via regulation of KEAP1/NRF2 signaling." (PMID 36719368, 2023). "It has also been shown that ROS accumulation activates the Keap1-Nrf2 signaling pathway in gastric cancer cells, thereby inhibiting apoptosis in gastric cancer cells." (PMID 36038533, 2022).